APC (APC regulator of Wnt signaling pathway)
Diseases named in the same sentence as APC in open-access papers (continued):
Sharing a sentence is not in itself a finding about the gene and the disease.
colorectal cancer (continued). "In human colorectal cancer cells with APC mutations, PrxII depletion consistently reduces the β-catenin levels and the expression of β-catenin target genes." (PMID 28659575, 2017). "Conversely, aberrant activation of the Wnt pathway, which occurs primarily through truncating mutations in APC, initiates the development of the vast majority of colorectal cancers." (PMID 28708826, 2017). "The majority of colorectal cancers originate from benign adenomas, which are caused by inactivating mutations in the adenomatous polyposis coli (APC) gene." (PMID 29254202, 2017). "Collectively, this study reveals a redox mechanism for regulating tankyrase activity and implicates PrxII as a targetable antioxidant enzyme in APC-mutation-positive colorectal cancer." (PMID 28659575, 2017). "Apc1572T harbors truncation mutation close to the MCR, and therefore is translated to APC protein that resembles that in human colorectal cancer." (PMID 28708837, 2017). "Further, the APC mutations that have been recognized as a hallmark of colorectal cancer were detected frequently in the CTC samples." (PMID 28978093, 2017). "ApcMin mice mimic familial colorectal cancer in patients with only one functional adenomatous polyposis coli (APC) gene allele, and APC is furthermore mutated in most sporadic human colorectal cancers." (PMID 29312533, 2017). "Here the authors show that in colorectal cancers with APC mutation, PrxII binds to tankyrase and prevents its oxidative inactivation, thereby preventing Axin1-dependent degradation of 2b-catenin." (PMID 28659575, 2017). "In colorectal cancers, the predominantly mutated component of this signaling pathway is the tumor suppressor gene APC with 85% occurring in a mutational “hotspot” region of the gene." (PMID 28587062, 2017). "The APC variant E1317Q, known to predispose to colorectal cancer was detected in a colon sample of one mummy." (PMID 26863316, 2016). "While wild type APC sequences were found in two mummies, we discovered the E1317Q missense mutation, known to be a colorectal cancer predisposing mutation, in a large intestine tissue of an 18th century mummy." (PMID 26863316, 2016). "The mutation of APC is reported in approximately 85% sporadic or familial colorectal cancer, and is regard as an initial event of CRC related with cancer cell adhesion and proliferation." (PMID 26760960, 2016). "Most cases of colorectal cancer (CRC) are initiated by inactivation mutations in the APC gene, which is a negative regulator of the Wnt-β-catenin pathway." (PMID 28010732, 2016). "About 80% of all colorectal cancers contain loss-of function mutations in the tumor suppressor gene APC." (PMID 26820295, 2016). "The loss of APC function because of deletion of putative promoter 1A or 1B also results in the development of colorectal cancer." (PMID 28105931, 2016). "APC (80-90%) and K-Ras (40-50%) mutations frequently occur in human colorectal cancer (CRC) and these mutations cooperatively accelerate tumorigenesis including metastasis." (PMID 27835580, 2016). "Colorectal cancer is initiated by dysregulation of the canonical WNT signaling cascade whereby mutations in the APC or CTNNB1 gene potentiate tumorigenesis in the colon." (PMID 27070088, 2016). "In contrast a high PITX2 protein expression, suggestive of a low or unmethylated PITX2 gene, is found in colorectal cancer where the WNT/β-Catenin is predominantly activated due to APC mutations." (PMID 27716615, 2016). "TNIK regulates Wnt signalling in the most downstream part of the pathway, and its pharmacological inhibition has been expected to block the signal even in colorectal cancer cells with mutation in the APC or CTNNB1 gene." (PMID 27562646, 2016). "Here, the authors sequence more than 1000 cancer genes in 468 colorectal cancers and show that mutation signatures can be used to classify the tumours and that multiple mutations in APC are associated with a poor prognosis." (PMID 27302369, 2016).
colorectal cancer (continued). "Given the high prevalence of APC mutation in sporadic colorectal cancer and APC being the causal gene for FAP, most of the models developed to mimic colon cancer have centred on models carrying APC mutation." (PMID 26414675, 2016). "Similar to the findings in colorectal cancer, APC promoter methylation is associated with various early- or late-stage human malignancies, including BC." (PMID 27478702, 2016). "APC is also inactivated by intragenic mutation in 70–80% of individuals with sporadic colorectal cancer." (PMID 27413734, 2016). "Studies examining the relationship between the APC E1317Q mutation and colorectal cancer have shown different results." (PMID 26863316, 2016). "It has also been proposed that RSPO2-LGR5 signaling has tumor-suppressive activity in colorectal cancer with APC mutations." (PMID 27338477, 2016). "APC (adenomatous polyposis coli) is an important component of the β-catenin destruction complex, which regulates Wnt signaling, and is often mutated in colorectal cancer (CRC)." (PMID 26884349, 2016). "One heterozygous variant, p.E1317Q, in the APC gene associated with a very modest 1.4-fold increased risk of colorectal cancer was identified in the germline of SC_9010 by both sequencing centers." (PMID 27167109, 2016). "Though plenty studies have investigated the APC role in the colorectal cancer carcinogenesis, the relationship between APC mutation and intestinal bacteria stimulation is still not well recognized." (PMID 26760960, 2016). "This deletion was accompanied by silencing of one of the APC alleles as well Hypermethylation of putative promoter 1A has also been reported for familial polyposis and human colorectal cancer." (PMID 28105931, 2016). "The multiple intestinal neoplasia (Min/+) mouse is frequently used as model for human FAP and colorectal cancer because it is heterozygous for a mutation in the tumor suppressor gene APC, which leads to the formation of numerous intestinal adenomas." (PMID 28002446, 2016). "Adenomatous polyposis coli (APC) is a multifunctional tumor suppressor protein and its mutation contributes to the progression of colorectal cancer (CRC)." (PMID 27144584, 2016). "This study has explored the interaction partners of colorectal cancer-associated genes, including adenomatous polyposis coli (APC)." (PMID 27011181, 2016). "Most recently, a role for L1 insertional activity was conclusively demonstrated for colorectal cancer caused by an insertion in the APC tumor suppressor gene." (PMID 27900322, 2016). "The Cancer Genome Atlas Research Network showed that 93% of colorectal cancers had mutations in this pathway; most often, these changes appeared in the APC tumor suppressor gene." (PMID 27047543, 2016). "Of note, the frequency of APC mutations in gastric adenomas in this study (100%) is comparable to those of colorectal cancers (~80% of MSS colorectal cancers), instead of those of gastric adenocarcinomas (<10%)." (PMID 27175599, 2016). "This was somewhat unexpected considering that mutations in the APC and β-catenin genes account for greater than 90% of all colorectal cancers, which is the second leading cause of death in the developed world." (PMID 27598201, 2016). "We reviewed the 5 patients’ lifetime EHRs and found the following results: (i) One male patient who carried a stop-gain mutation (rs72953290) in APC had prostate cancer, many colon polyps, and colorectal cancer." (PMID 27930734, 2016). "Familial adenomatous polyposis (FAP) is a dominantly inherited syndrome caused by germline mutations in the APC gene and characterized by the development of multiple colorectal adenomas and a high risk of developing colorectal cancer (CRC)." (PMID 26880076, 2016). "APC (adenomatous polyposis coli) was originally identified as a gene mutated in colorectal cancers associated with the FAP syndrome, hence the name." (PMID 28105931, 2016).
colorectal cancer (continued). "Similar to our observations, SIRT1-deficiency reduced polyp area and size in the APC+/min model of colorectal cancer and reduced the number and the size of tumors in a colitis-induced colorectal cancer model." (PMID 27494892, 2016). "To assess the presence of genetic predisposition to colorectal cancer in the pre-industrialization era we attempted to amplify the MCR region of the APC gene from DNA obtained from internal organs of the Vác mummies." (PMID 26863316, 2016). "Based on the present study, we found cell proliferation of APC mutation colorectal cancer cells was accelerated with LPS stimulation." (PMID 26760960, 2016). "While APC is highly relevant with respect to chromosomal aberrations in human colorectal cancers, mutations in APC are rare in human prostate cancer." (PMID 27898031, 2016). "Here we used the Vác mummies to assess the existence of genetic predisposition to colorectal cancer in the pre-industrialization era by sequencing of “hot spots” in the APC gene." (PMID 26863316, 2016). "According to the theory, the earliest event in the colorectal cancer involves the mutation of APC gene." (PMID 27121310, 2016). "Aberrant activation of Wnt-β-catenin signaling (by stabilizing mutations in β-catenin, or in the adenomatous polyposis coli, APC, gene) is a hallmark of colorectal cancer (CRC) development in the majority of colon cancer patients." (PMID 27187476, 2016). "In colorectal cancers where Wnt/β-catenin signaling is frequently activated by mutated APC or β-catenin, it seems that, for antitumor efficacy, the ideal antagonist of the pathway would be targeting the transcriptional complex of TCF and β-catenin." (PMID 26862734, 2016). "NCB-0846 inhibited the TCF/LEF transcriptional activity of Wnt3a-treated HEK293 and HCT116 (carrying CTNNB1 mutation) and DLD-1 (carrying APC mutation) colorectal cancer cells." (PMID 27562646, 2016). "One gene associated with schizophrenia has been the adenomatous polyposis coli (APC) gene; a tumor suppressor gene that increases one’s risk for cancer, specifically, colorectal cancer and familial adenomatous polyposis (FAP)." (PMID 26436104, 2015). "Here we report that mutations in adenomatous polyposis coli (APC) found in colorectal cancer activate cell stress pathways in mouse intestinal crypt cells, prior to loss of heterozygosity at APC or to the appearance of canonical intestinal cancer markers." (PMID 26320184, 2015). "Min mice, as in the majority of human colorectal cancers, express a monoallelic APC mutation that encodes for a truncated protein and this single allele is sufficient to drive the formation of intestinal adenomas." (PMID 26320184, 2015). "Other patients had only modest degrees of imbalances of APC, which, as previously discussed, increase the risk of colorectal cancer." (PMID 26511139, 2015). "As a first test of these predictions, we focused on driver mutations in the adenomatous polyposis coli (APC) tumor suppressor that contribute to both familial and sporadic human colorectal cancer." (PMID 26320184, 2015). "We identified only one pathogenetic mutation of APC in a 34-year-old patient with colorectal cancer and polyposis." (PMID 26557847, 2015). "This conclusion was further supported by testing colorectal cancer cell lines in which canonical Wnt signaling is constitutively active due to mutations either in β-catenin (HCT116 line) or in APC (DLD1 line)." (PMID 26110841, 2015). "For example, APC mutations are reported at a much lower frequency in SBA (5%) compared to colorectal cancer (80%)." (PMID 26315110, 2015). "Depending on ethnicity, geographical region, dietary, and genetic predisposition and mostly because of heterogeneous nature of colorectal cancer, APC mutation genes are considerably diverse and distinct, as well as in sporadic CRCs." (PMID 25685149, 2015).
colorectal cancer (continued). "Even in colorectal cancer it was shown that in cells from the same tumours, all assumed to have the same initiating loss of APC or oncogenic activation of β-catenin, dynamic localisation changes between nucleus and cytoplasm can be found." (PMID 25647637, 2015). "Hsf1 is the master regulator of the heat shock response and our findings argue that APC mutants associated with human colorectal cancer activate Hsf1." (PMID 26320184, 2015). "The mutation rate of APC in large intestine cancers is much higher than that of CTNNB1, and the samples harboring APC mutations contained most of those harboring CTNNB1 mutations (78 of 99)." (PMID 26212640, 2015). "The tumor suppressor gene, APC (adenomatous polyposis coli), has been extensively investigated and linked to colorectal cancer development." (PMID 26394139, 2015). "We now know that RSPO2 fusion genes occur in a subset of colorectal carcinomas and are mutually exclusive with APC mutations." (PMID 26115037, 2015). "Apcmin/+ mice are representative of hereditary and rare forms of colorectal cancer, based on mutations in the APC gene." (PMID 25013930, 2014). "Loss of function and mutation of APC in colorectal cancer or GSK-3 in gastric cancer disrupts the function of the destruction complex and liberates β-catenin." (PMID 24589238, 2014). "The dysregulation of Wnt signaling pathway is the most frequent event observed in colorectal cancer, which is usually manifested by inactivating mutations of APC or activating mutations of β-catenin." (PMID 25025473, 2014). "Mutations in APC (Adenomatous polyposis coli) gene are known to be associated with Familial adenomatous polyposis coli and colorectal cancer." (PMID 24790823, 2014). "Our study reports unsatisfactory level of residents' knowledge on genetic tests for colorectal cancer and on prevalence of hereditary forms and penetrance of APC mutations." (PMID 25050348, 2014). "Further, most sporadic colorectal cancers acquire somatic APC mutations and the pattern of somatic genetic changes is consistent with APC being a tumor suppressor gene." (PMID 24416237, 2014). "Nevertheless, this population has a greater chance of producing an inactive APC gene in somatic tissues, which increases the risk of colorectal cancer." (PMID 25033203, 2014). "The adenomatous polyposis coli (APC) tumor suppressor is the most commonly mutated gene in colorectal cancers." (PMID 25275295, 2014). "Although the APC gene encodes a major tumor suppressor gene for colorectal cancer, and APC mutations have been found in some other cancers, inactivating mutations in the APC gene are rare in human CaP." (PMID 24651496, 2014). "The APC mutations in breast cancers are typically found at sites distinct from the APC mutation cluster region in colorectal cancers and are much more frequently seen in advanced than early stage breast cancers." (PMID 25406066, 2014). "In colorectal cancer cells, frequent mutations are observed in APC, the responsible gene for familial adenomatous polyposis of the colon, and β-catenin (CTNNB1)." (PMID 24466159, 2014). "The APC (Adenomatous Polyposis Coli) gene encodes a tumor suppressor that is inactivated in a large proportion of human colorectal cancers." (PMID 24651496, 2014). "Residents knowledgeable on genetic tests for colorectal cancer, prevalence of hereditary forms, and penetrance of APC mutations were 21.2% (77/364)." (PMID 25050348, 2014). "There has been much discussion of when chromosomal instability occurs, for example some have suggested it as a key facilitator of early tumorigenesis, notably causing loss of heterozygosity of APC in colorectal cancers." (PMID 23762276, 2013). "In several studies over-expression (Cyclin D1, NF-κB, PCNA, MMP-2) or loss of expression (Bcl-2, APC) of these molecules have been found to be associated with more aggressive tumor growth in colorectal cancer." (PMID 23326301, 2013).
colorectal cancer (continued). "APC mutations occur in most colorectal cancers and typically result in truncation of the C-terminal half of the protein." (PMID 24156781, 2013). "For n = 2 (an appropriate biological value only if the loss of both copies of the APC gene were necessary and sufficient for initiation in most colorectal cancers) and m = 1 as default assumptions the GOF(h,t) was 0.085." (PMID 24195059, 2013). "Using liposomes as vectors, a complete functional APC gene was introduced into a colorectal cancer cell (SW480) line derived from the large intestine with a mutated APC gene." (PMID 24148210, 2013). "In most sporadic colorectal cancers, mutations in APC prevent the ubiquitination of β-catenin, which is a transcription factor involved in cell proliferation." (PMID 24324931, 2013). "In “sporadic” colorectal cancer (CRC) these neoplasms occur as a result of a mutation in one of the APC alleles followed by a loss of heterozygosity as a result of somatic mutations." (PMID 24148210, 2013). "Colorectal cancer is the fourth leading cause of cancer related deaths worldwide, and a key genetic change associated with this disease is mutation of the gene APC." (PMID 23935526, 2013). "MCC is also an intriguing HCC candidate gene because of its genomic proximity to APC, a major tumor suppressor mutated in familial adenomatous polyposis preceding colorectal cancer." (PMID 23540693, 2013). "We asked the question, how can the effects of APC truncation, a very common mutation in colorectal cancer, be understood and reversed?" (PMID 24086117, 2013). "Colorectal cancer is generally considered to progress from adenoma to carcinoma, with APC and KRAS mutations occurring early; APC mutations in the normal epithelium and KRAS somewhere along the transition from small to medium size adenoma." (PMID 24066160, 2013). "One prediction from these data is that, in contrast to exclusively driving tumor initiation as known to do in colorectal cancer for example, APC loss would actually prevent primary tumor invasion or metastasis to a distant site." (PMID 23302090, 2013). "APC is a well-known tumour suppressor gene in human colorectal cancer, and APC mutations in mice are associated with neoplasm formation." (PMID 23940460, 2013). "Mutations in Wnt/adenomatous polyposis coli (APC)/β-catenin (CTNNB1) signaling pathway members have been found in many colorectal carcinomas." (PMID 23405266, 2013). "It is important to note that mutated APC occurs in <2% of HCC cases versus >60% of colorectal carcinomas." (PMID 23540693, 2013). "We conclude that the expansion of colorectal cancer cell lines can be inhibited by RNA interference against APC in an allele-specific manner." (PMID 22509309, 2012). "The tumour suppressor gene adenomatous polyposis coli (APC) is mutated in most colorectal cancer cases, leading to the synthesis of truncated APC products and the stabilization of β-catenin." (PMID 22509309, 2012). "In cancer contexts such as colorectal cancer where upregulated WNT/β-catenin is mediated by constitutively activating downstream mutations in CTNNB1 or APC, therapeutic approaches to modulating WNT/β-catenin signalling have been somewhat limited." (PMID 23129487, 2012). "Loss of function mutations in the tumour suppressor APC are by far the most common and can be found in a high percentage of colorectal cancers." (PMID 22919349, 2012). "In colorectal cancer cells, which typically harbor APC mutations, inhibition of tankyrase activity promotes Axin stabilization and attenuates Wnt signalling." (PMID 23144924, 2012).